CCL5 (C-C motif chemokine ligand 5)
Diseases named in the same sentence as CCL5 in open-access papers (continued):
Sharing a sentence is not in itself a finding about the gene and the disease.
keratoconus (4 papers, 2011 to 2018). A degenerative, structural disorder of the eye, characterized by a cone-shaped protrusion of the cornea. "Levels of IL-6 and IL-17 were increased, while IL-12, CCL5, and IL-13 were decreased in keratoconus tear fluids compared with control." (PMID 27403376, 2016). "The decreases in IL-12, TNF-α and CCL5 were statistically significant, while the IL-13 decrease was statistically significant in the severe keratoconus group only." (PMID 21298010, 2011). "Interleukin (IL)-1β, IL-4, IL-6, IL-10, IL-12, IL-13, IL-17, interferon (IFN)-γ, chemokine C-C motif ligand 5 (CCL5) and tumor necrosis factor (TNF)-α were tested in tear samples and sera of keratoconus and control individuals by multiplex immuno-bead assays." (PMID 21298010, 2011). "In the current study, we have determined the associations between nine mediators (IL-6, IL-10, CXCL8/IL-8, CCL5/RANTES, MMP-9, MMP-13, TIMP-1, t-PA, and PAI-1) in the tear fluid of keratoconic patients covering the whole spectrum of the disease (from subclinical to manifest keratoconus)." (PMID 26881061, 2016).
leishmaniasis (4 papers, 2012 to 2023). Infectious disease that is transmitted through the bite of hematophagous female phlebotomine sand flies. "Increased CCL-5 expression has also been found in the skin and spleen of dogs with leishmaniasis, and is positively correlated to parasite load." (PMID 37443858, 2023). "The role of CC-chemokines CCL2, CCL3 and CCL5 in leishmaniasis has been tested in a number of studies." (PMID 22679519, 2012). "The observed strain differences and the double peak of CCL3 and CCL5 in CcS-16 females provide a novel potential starting point for investigation of the impact of inter-individual differences in chemokine response on pathogenesis of leishmaniasis." (PMID 22679519, 2012). "It has been proposed that in leishmaniasis, chemokines CCL2, CCL4, and CCL5 generally play a role not only as chemotactic factors but also as co-activators of macrophages and consequently have a part in the elimination of parasites." (PMID 22506080, 2012).
leprosy (4 papers, 2021 to 2025). Leprosy is a chronic infectious disease affecting primarily the skin and peripheral nervous system. "One of these genes, CCL5/RANTES, is a key chemoattractant for monocytes in the skin suggesting a pro-inflammatory feedback loop during M. leprae infection toward M1-like macrophages, which is consistent with the higher expression in PB leprosy." (PMID 33936067, 2021).
lymphopenia (4 papers, 2007 to 2024). Reduction in the number of lymphocytes. "Parallels seen in late-stage disease mice include: high viral loads (RNAemia), elevated AST and ALT, elevated neutrophils, lymphopenia, and increases in IL-10, IL-6, IFN-γ, CCL2, CCL5, and TNF-α." (PMID 31790513, 2019).
memory impairment (4 papers, 2017 to 2025). "However, CCL5 has also been shown to have pro-inflammatory effects on microglia, and its overexpression has been associated with memory impairment in mice." (PMID 40656548, 2025). "The C-C chemokine receptor type 5 (CCR5), which binds ligands like CCL5, has emerged as a key element in modulating network function through synaptic pruning, potentially contributing to observed learning and memory impairments." (PMID 39171200, 2024). "Most of the CCL5-KO mice showed memory impairment at age of 4 months." (PMID 33931731, 2021).
meningitis (4 papers, 2011 to 2025). A disorder characterized by acute inflammation of the meninges of the brain and/or spinal cord. "In a patient with a flu-like TBEV infection, CCL5 in the csf was close to the lower end of values found in TBE meningitis/meningoencephalitis but still higher than in any of the control samples." (PMID 26906062, 2016). "Median CCL5 was significantly higher in patients with meningoencephalomyelitis in comparison with meningitis and meningoencephalitis groups." (PMID 26906062, 2016). "In meningoencephalitis, CCL5 concentration was not different in comparison with the meningitis group and did not depend on the severity of the cns involvement." (PMID 26906062, 2016).
metastatic colorectal cancer (4 papers, 2016 to 2023). "Among the subjects with metastatic colorectal cancer (mCRC), the carriers of any G allele in CCL5 rs2280789, who had received cetuximab plus FOLFIRI, demonstrated shorter OS when compared to AA homozygotes." (PMID 38001676, 2023).
migraine (4 papers, 2018 to 2025). "Similarly, another study showed that the expression of RANTES gene (CCL5) is upregulated during migraine attacks, contributing to platelet activation." (PMID 35883701, 2022). "Similarly, CCL5 (RANTES) was found at significantly higher levels in blood serum from migraine patients during a headache attack, compared with healthy controls and with samples taken 1 week later from the same patients." (PMID 35295531, 2021). "Additionally, differential expression of CCL3 and CCL5 has been reported to be able to be used to distinguish between patients with migraine and those with tension-type headache." (PMID 35295531, 2021).
myocardial ischemia (4 papers, 2015 to 2022). A disorder of cardiac function caused by insufficient blood flow to the muscle tissue of the heart. "Neutralizing anti-CCL5 antibodies have provided a therapeutic benefit in a mouse model of chronic cardiac ischemia." (PMID 35784739, 2022).
non-alcoholic fatty liver disease (4 papers, 2019 to 2021). "Moreover, a recent systematic review and meta-analysis suggested that the chemokines, CCL3, CCL4, CCL5, CCL20, CXCL8 and CXCL11, are implicated in the pathogenesis of non-alcoholic fatty liver disease, post-traumatic stress disorder, and also different types of cancers." (PMID 35242125, 2021). "Moreover, a recent systematic review and meta-analysis suggested that chemokines, CCL3, CCL4, CCL5, CCL20, CXCL8 and CXCL11, are implicated in the pathogenesis of non-alcoholic fatty liver disease, post-traumatic stress disorder, and also different types of cancers." (PMID 34054797, 2021).
post-traumatic stress disorder (4 papers, 2020 to 2021). An anxiety disorder precipitated by an experience of intense fear or horror while exposed to a traumatic (especially life-threatening) event. "Clinical studies have demonstrated an increase in CCL5 and CCL2 serum levels in subjects displaying generalized anxiety disorder, chronic stress, and post-traumatic stress disorder (PTSD)." (PMID 34863117, 2021). "In the same line, related studies showed an increase in ENA-78/CCL5 and MCP-1/CCL2 serum levels in subjects displaying generalized anxiety disorder, chronic stress, and post-traumatic stress disorder." (PMID 34863117, 2021).
Pruritus (4 papers, 2022 to 2025). Pruritus is an itch or a sensation that makes a person want to scratch. "Among the studied chemokines (C-C Motif Chemokine Ligand (CCL) 2/MCP-1, CCL3/MIP-1α, CCL4/MIP-1β, CCL5/RANTES, CXCL8/IL-8, CCL17/TARC, CCL18/PARC, CCL22/MDC), only CCL17/TARC showed a positive correlation with pruritus intensity." (PMID 37834183, 2023). "The aim of the study was to analyse serum concentrations of CCL2/MCP-1, CCL3/MIP-1α, CCL4/MIP-1β, CCL5/RANTES, CCL17/TARC, CCL18/PARC, CCL22/MDC and CXCL8/IL-8, and their correlation with PsO severity and pruritus intensity." (PMID 36362116, 2022).
pulmonary sarcoidosis (4 papers, 2011 to 2025). Sarcoidosis affecting the lung parenchyma. "Conversely, we found an association between elevated BALF protein levels of CCL5 and pulmonary sarcoidosis." (PMID 21463523, 2011). "Moreover, our results are supported by other smaller investigations that have also found BALF proteins levels of CCL5 to be associated with pulmonary sarcoidosis." (PMID 21463523, 2011). "In an effort to clarify discrepancies between these studies, we performed the largest observational study involving BALF CC chemokines (CCL2, CCL3, CCL4, and CCL5) during the pathogenesis of pulmonary sarcoidosis." (PMID 21463523, 2011). "Likewise, CCL2 and CCL5 are elevated in other diseases, such as pulmonary sarcoidosis or the synovial fluid of patients with juvenile rheumatoid arthritis." (PMID 39781111, 2025). "Our analysis therefore nominated CCL2 and CCL5, both chemoattractants of mononuclear and mast cells, as well as CCL19, a chemokine implicated in T-lymphocyte recruitment, as key candidate chemokines associated with prognosis of pulmonary sarcoidosis." (PMID 26696750, 2015). "However, CCL2 and CCL5 levels were elevated, and subgroup analysis showed higher levels of both chemokines in all stages of pulmonary sarcoidosis." (PMID 21463523, 2011).
skin cancer (4 papers, 2021 to 2025). "The supernatants of these ex vivo cultured tumors were quantitatively screened for cytokines, chemokines, and growth factors, identifying CCL5 and GM-CSF, molecules associated with skin cancer metastasis, to be markedly decreased." (PMID 34768877, 2021). "In addition, we observed a higher expression of PD-1 (encoded by Pdcd1), Itga4, Sell, and Ccl5 in skin tumors." (PMID 40282557, 2025). "Consistent with its enhanced immunosuppressive role, Tregs in skin tumors presented higher levels of Itga4, Sell, and Ccl5." (PMID 40282557, 2025). "There are many sources of CCL5 in skin cancer, for instance, dendritic cells, macrophages, cancer-associated fibroblasts, keratinocytes, mast cells, and tumor cells." (PMID 34768877, 2021). "CXCL17, CCR2, and CCL5 mRNA levels were significantly decreased in skin tumors of CCL17 TG mice compared with WT mice." (PMID 33670758, 2021).
small cell lung carcinoma (4 papers, 2021 to 2024). Small cell lung cancer (SCLC) is a highly aggressive malignant neoplasm, accounting for 10-15% of lung cancer cases, characterized byrapid growth, and early metastasis. "For example, in small cell lung cancer (SCLC), a WEE1 inhibitor induced DNA damage in cancer cells, increasing type I interferons, CCL5 and CXCL10 via activation of the cGAS-STING pathway, enhancing the response to PD-L1 blockade." (PMID 38796460, 2024). "In a similar study, the Chk1 inhibitor SRA737 in combination with low dose gemcitabine increased CCL5, IFN-β and CXCL10 mRNA expression in small cell lung cancer again indicative of Chk1i activating a Type I IFN response." (PMID 35006469, 2021). "This current work is in direct contrast to previously published work demonstrating that Chk1 inhibition in small cell lung cancer cells increased TBK1 and IRF3 phosphorylation, CCL5, IFN-β and CXCL10 mRNA expression, and elevated PD-L1 expression all indicative of a type I IFN response." (PMID 35006469, 2021).
tauopathies (4 papers, 2023 to 2025). "recently showed that the cytokine receptor CCR5 (which binds IFN‐I‐associated ligands for MIP‐1a/CCL3, MIP‐1b /CCL4, and CCL5) promoted tauopathy in in vivo models, partially through the regulation of autophagy." (PMID 37849026, 2024). "The activated microglial CCL5 to neuronal CCR5 signaling exacerbates protein aggregation in tauopathy." (PMID 37941028, 2023).
Ureteral obstruction (4 papers, 2014 to 2023). Obstruction of the flow of urine through the ureter. "Crisman and coworkers detected the expression of CCL2/MCP-1, CCL5/RANTES, and CXCL10/IP-10 at 1 day of unilateral ureteral obstruction in mice." (PMID 24692841, 2014).
alcohol (3 papers, 2006 to 2023). "Consistent with this, we observed decreased expression of natural killer cell-related genes, including CD44, IL15R, CD2 and CCL5, in alcohol-associated cirrhotic liver samples." (PMID 17121680, 2006).
allergic rhinitis (3 papers, 2010 to 2014). Inflammation of the nasal mucous membranes caused by an IgE-mediated response to external allergens. "Inhibition of CCL5-dependent recruitment of cells to diseased airway tissue, and reduced cell proliferation, reduced general cell apoptosis, but not increased eosinophil apoptosis, are involved in early phase steroid-induced resolution of human allergic rhinitis." (PMID 20459697, 2010).
aortic aneurysm (3 papers, 2016 to 2024). A ruptured aneurysm located in the wall of the proximal portion of the descending aorta proceeding from the arch of the aorta. "Indeed, a significant relationship between the pathogenesis of AAA and serum IL-1β and CCL5 levels has been reported, indicating that aortic aneurysm formation and progression could be blocked by genetic or pharmacological inhibition of IL-1β or CCL5." (PMID 37205167, 2022).
astrocytoma (3 papers, 2016 to 2022). "While below the detectable limit in normal cortex, chemokine C–C ligand 5 (CCL5) and vascular endothelial growth factor (VEGF) concentrations were increased in high-grade astrocytoma (64.8 ± 34 pg/mL; **P < .01; 57.7 ± 12 pg/mL; **P < .001)." (PMID 34131649, 2021).
benign prostatic hyperplasia (3 papers, 2017 to 2020). A non-cancerous nodular enlargement of the prostate gland. "In prostate tissue of BPH (benign prostatic hyperplasia) patients undergoing 5α-reductase type II inhibitor treatment with finasteride leading to reduced intraprostatic DHT levels, a stronger infiltration of CD8+ T cells and higher CCL5 expression was observed." (PMID 32849531, 2020).
brain inflammation (3 papers, 2012 to 2023). "Brains were homogenized and intracranial levels of three cytokines known to be associated with and/or causative for HSV-1 mediated brain inflammation and that are also linked with the outcome of HSV-1 encephalitis, IL-6, CCL5 (Rantes) and CCL2 (MCP-1) were measured." (PMID 23082204, 2012).
chlamydial infection (3 papers, 2008 to 2018). "Taken together with other studies, the data show that CCL5 mediates the temporal recruitment and activation of leukocytes to mitigate chlamydial infection through enhancing adaptive mucosal humoral and cellular immunity." (PMID 18700040, 2008). "The extent of chlamydial infection, determined by C. muridarum detected in cervico-vaginal swabs, was significantly higher in mice receiving anti-CCL5 Ab treatment than compared to control mice." (PMID 18700040, 2008). "Understanding the cellular and molecular mechanisms that CCL5 uses to modulate mucosal immunity is essential to better understanding the pathogenesis of chlamydial infection." (PMID 18700040, 2008). "Our data suggest that CCL5 interactions are comparably important and mediate the temporal recruitment and activation of T cells to mitigate chlamydial infection through protective mucosal adaptive immunity by enhancing Th1 >> Th2 humoral and cellular immune responses." (PMID 18700040, 2008). "CCL3 and CCL4 are also CCR5 ligands, but these chemokines were not remarkably elevated compared to CCL5, which was the most abundant CCR5 ligand expressed during the early stages (i.e., < 7 days) of chlamydial infection." (PMID 18700040, 2008).
cholangiocarcinoma (3 papers, 2017 to 2022). A carcinoma that arises from the intrahepatic biliary tree (intrahepatic cholangiocarcinoma) or from the junction, or adjacent to the junction, of the right and left hepatic ducts (hilar cholangiocarcinoma). "Then a migration assay was performed to investigate whether MSCs promoting cholangiocarcinoma cell migration and invasion was associated with high expression level of CCL5." (PMID 29088737, 2017). "In our present study, MSCs under inflammatory condition exhibited higher expression levels of CCL5 than control MSCs cells, and co-culture of cholangiocarcinoma cells with MSC(TI)-CM induced upregulation of CCR1, CCR3 and CCR5 expression." (PMID 29088737, 2017).
chronic hepatitis C (3 papers, 2007 to 2017). "Furthermore, CCL3, CCL4, CCL5, CXCL9, CXCL10 and CXCL11 were found to increase in both liver and peripheral blood during chronic hepatitis C in several studies." (PMID 29284412, 2017).
congestive heart failure (3 papers, 2016 to 2021). Failure of the heart to pump a sufficient amount of blood to meet the needs of the body tissues, resulting in tissue congestion and edema. "In fact, many factors such as CCL-2, CCL-3, and CCL-5, whose gene expression was highly increased in preconditioned MSCs, were reported to be upregulated in patients with structural remodeling including hypertrophy and congestive heart disease." (PMID 33927770, 2021).
coronary stenosis (3 papers, 2016 to 2023). Narrowing of the coronary artery lumen diameter. "In our study, CCL5 was independently associated with the presence of ≥50 % coronary stenosis, a well-known risk factor for the occurrence of a cardiac event." (PMID 27573044, 2016).
dysplasia (3 papers, 2021 to 2023). A usually neoplastic transformation of the cell, associated with altered architectural tissue patterns. "The transcript levels of Th1-associated chemokines/cytokines (Cxcl9, Cxcl10, Ccl5, and Ifng) and the Th1-associated chemokine receptor Cxcr3 were upregulated in dysplasia, whereas the expression of these Th1-associated genes was decreased in SCC." (PMID 33921389, 2021).
emphysema (3 papers, 2018 to 2022). "Experimental animal studies have shown that the severity of cigarette smoke-induced emphysema is greatly attenuated in CCR5-deficient mice, and monocytes from patients with COPD exhibit enhanced migration in response to CCL5." (PMID 29907106, 2018).
encephalomyelitis (3 papers, 2016 to 2024). Inflammation of the brain and the spinal cord. "Besides rabies, CCL5 plays a major role in leukocyte recruitment during herpes virus- and West Nile virus-induced encephalomyelitis." (PMID 34804996, 2021).
endometrial tumor (3 papers, 2021 to 2025). "Other produced cytokines in the endometrial tumor environment include IL-6, IL-8, monocyte chemotactic protein-1 (MCP-1 or CCL2), chemokine ligand 5 (CCL5 or RANTES) and vascular endothelial growth factor (VEGF)." (PMID 41228294, 2025).
endotoxemia (3 papers, 2009 to 2026). "Moreover, we analyzed pro-inflammatory cytokines and chemokines in the plasma of Cdk5LysMCre and Cdk5flox mice during LPS-induced endotoxemia, since in vitro studies using c-Maf knockout macrophages showed elevated levels of Ccl5 and Il-1a in addition to Il-10." (PMID 34502552, 2021).
enterovirus infection (3 papers, 2013 to 2017). "Similarly, intestinal CCL5 production was also demonstrated following enterovirus infection." (PMID 28579989, 2017). "Analysis of the cytokine/chemokine-profile following enteroviral infection with a cytometric bead array and Q-PCR revealed an enhanced secretion of PanGRO (CXCL1, CXCL2 and CXCL3), IL8 and CCL5." (PMID 23305147, 2013).
esophageal cancer (3 papers, 2020 to 2024). A primary or metastatic malignant neoplasm involving the esophagus. "In gastric and esophageal cancer, CCL5 secreted by lymph node-derived cells recruits CCR5 + Tregs to the tumor lesion." (PMID 38937380, 2024).
Ewing sarcoma (3 papers, 2022 to 2024). A small round cell tumor that lacks morphologic, immunohistochemical, and electron microscopic evidence of neuroectodermal differentiation. "In Ewing sarcoma, the expression of CCR5-ligand, CCL5, is positively related to the number of infiltrating CD8+ T-lymphocyte and patients with high numbers of infiltrating T-lymphocytes have an overall survival advantage." (PMID 36092920, 2022).
fibrosarcoma (3 papers, 2015 to 2022). A malignant mesenchymal fibroblastic neoplasm affecting the soft tissue and bone. "Nevertheless it has to be remarked that TAMs from murine fibrosarcoma model upon LPS treatment showed also typical M1 IFN-inducible cytokine expression: CCL5 (also known as RANTES), CXCL9, CXCL10, and CXCL16 due to active IRF3-dependent pathway." (PMID 28197019, 2017).
gastritis (3 papers, 2018 to 2024). Inflammation of the stomach. "First, within the gastric mucosa of patients infected with H. pylori, positive correlations between ANGPTL4 and CCL5 as well as between CCL5 and Foxp3 were found, and CCL5 was also increased and was found to be positively correlated with the severity of gastritis." (PMID 39022746, 2024).